FBN1 (fibrillin 1)
Diseases named in the same sentence as FBN1 in open-access papers (continued):
Sharing a sentence is not in itself a finding about the gene and the disease.
vascular Ehlers-Danlos syndrome (5 papers, 2023 to 2025). "Additional genes include those involved in ECM function and homeostasis, including Fibrillin-1 (Fbn1), Lysyl oxidase (Lox), Biglycan (Bgn) associated with MFS, Procollagen type III α1 (Col3a1) associated with vascular EDS and Elastin (Eln) usually associated with CLS." (PMID 39768700, 2024).
colon carcinoma (4 papers, 2011 to 2021). "The genetic mutation of FBN1 is also associated with colon cancer." (PMID 30186855, 2018). "For example, hypermethylation of Synuclein Alpha (SNCA) and FBN1 in stool samples show excellent sensitivity and specificity for colon cancer." (PMID 34386072, 2021). "FBN1 is an extracellular matrix glycoprotein and high methylation in colonic tissue of patients with colon cancer." (PMID 30186855, 2018). "It is noted that FBN1 has been identified as a promising early detection biomarker of colon cancer and colon adenomas." (PMID 30186855, 2018). "Four genes that are involved in calcium binding or signaling were co-regulated with TAZ-AXL-CTGF in the colon cancer specimens, including FBN1, CALD1, MGP and MYL9." (PMID 23372686, 2013). "Interestingly, multiple genes involved in calcium signaling (FBN1, CALD1, MGP and MYL9) were co-overexpressed with TAZ-AXL-CTGF in colon cancer." (PMID 23372686, 2013). "Before drug treatment all colon cancer cell lines tested harbored promoter methylation of CNRIP1, INA, FBN1, and SNCA accompanied by little or no expression of the same genes." (PMID 21777459, 2011).
congenital heart disease (4 papers, 2014 to 2025). A heart disease that is present at birth. "Previous studies on various congenital heart diseases have confirmed that the pathways of FBN1 gene mutations leading to changes in cardiac structure are multi-faceted." (PMID 40959563, 2025). "Among these, FBN1 and LZTR1 are well-known risk genes implicated with syndromes that include heart defects." (PMID 32349777, 2020).
cystic fibrosis (4 papers, 2009 to 2025). Autosomal recessive disorder caused by pathogenic variants in the CFTR gene (cystic fibrosis transmembrane conductance regulator), which encodes a chloride and bicarbonate channel expressed in epithelial cells, and follow the diagnosis criteria. "These proteins included Serpin Family B Member 12 (SERPINB12), and fibrillin-1 (FBN1), proteins associated with cystic fibrosis and connective tissue disease." (PMID 40508199, 2025).
diabetes (4 papers, 2021 to 2025). "In addition to our previous review of the crucial role of asprosin, here we showed that oxytocin could ameliorate obesity-induced diabetes and decrease FBN1 gene expression centrally to block appetite." (PMID 35462799, 2022). "Therefore, the genetic expression of FBN1 and PEPCK enzyme activity in diabetic rats and after oxytocin therapy indicated the possibility that asprosin could be a biomarker of diabetes progression." (PMID 35462799, 2022).
long QT syndrome (4 papers, 2023 to 2024). "Two patients with secondary findings in FBN1 and KCNQ1 were confirmed to have previously unidentified Marfan and long QT syndromes, respectively, and were referred for further clinical interventions." (PMID 37946251, 2023).
renal fibrosis (4 papers, 2019 to 2025). A final common manifestation of a wide variety of chronic kidney diseases characterized by glomerulosclerosis and tubulointerstitial fibrosis. "Among them, the functions of Fn, Timp1, C3, Apoe, Trf, and Fbn1 were already previously thoroughly studied in renal fibrosis." (PMID 40564035, 2025). "Recent data also show that fibrillin-1 induces endothelial cell apoptosis, inhibits their proliferation and contributes to vascular rarefaction and renal fibrosis in chronic kidney disease." (PMID 33807627, 2021). "The expression of its targets including Collagen 1A1 and Fibrillin 1 as well as renal fibrosis was significantly increased." (PMID 31658856, 2019). "On the other hand, it has been demonstrated that FBN1 is overexpressed in renal tissue and that its deletion decreases the injury and fibrosis induced by unilateral ischemia-reperfusion injury (UIRI) in a murine model of renal fibrosis." (PMID 34440261, 2021).
Arrhythmia (3 papers, 2013 to 2021). Any cardiac rhythm other than the normal sinus rhythm. "Most importantly, it remains to be clarified, whether arrhythmia may be viewed as a primary consequence of FBN1 mutation characteristics itself, or whether arrhythmia is a result from secondary conditions such as myocardial ischemia, mitral valve abnormality, or ventricular dysfunction." (PMID 24349050, 2013).
bladder cancer (3 papers, 2019 to 2021). "High expression of FBN1 has been reported in bladder cancer patients and associated with worst overall survival." (PMID 32922663, 2020). "Similarly, elevated FBN1 expression in both colon and bladder cancer are associated with worse overall survival." (PMID 34386072, 2021). "Survival analysis of bladder cancer patients revealed elevated expression COL6A1 and FBN1 is associated with a worse overall survival and progression of disease." (PMID 32922663, 2020).
cataract (3 papers, 2019 to 2024). Partial or complete opacity of the crystalline lens of one or both eyes that decreases visual acuity and eventually results in blindness. "Thereafter, prevalence increased such that, by 1 year, 86% of eyes from Fbn1-NPCE mice had dense cortical cataracts." (PMID 30642872, 2019). "In conclusion, we have shown that, in mice, disrupting Fbn1 expression in the nasal/temporal regions of the NPCE is sufficient to produce EL, cataract and buphthalmia." (PMID 30642872, 2019).
chronic kidney disease (3 papers, 2021 to 2025). Impairment of the renal function secondary to chronic kidney damage persisting for three or more months. "Our findings revealed that FBN1 was significant upregulated in the decellularized kidney tissue scaffold in chronic kidney disease (CKD)." (PMID 38269088, 2023). "We identified the hub genes of CKD (Fn, Timp1, C3, Apoe, Trf, Fbn1, FGG, Penk, Ckap4, and Gpc3) through multiple bioinformatics analyses and successfully verified their expression in a mouse chronic kidney disease model." (PMID 40564035, 2025).
collagenopathy (3 papers, 2021 to 2025). "Bilateral RRD was only seen in collagenopathies/vitreoretinopathies with COL2A1 (n = 2, 33.3%), COL11A1 (n = 1, 16.7%), COL18A1 (n = 1, 16.7%) and FBN1 (n = 2, 33.3%) genotypes." (PMID 41465105, 2025).
fibrosis (3 papers, 2017 to 2022). the formation of excess fibrous connective tissue in an organ or tissue in a reparative or reactive process. "Due to a duplication mutation in FBN1, Tsk1/+ mice spontaneously develops fibrosis of the skin." (PMID 36136452, 2022). "Due to a fibrillin-1 gene tandem duplication mutation, Tsk1/+mice spontaneously develop fibrosis of the skin in the absence of inflammation and vascular changes." (PMID 36289219, 2022).
idiopathic pulmonary fibrosis (3 papers, 2023). Idiopathic pulmonary fibrosis (IPF) is a nonneoplastic pulmonary disease that is characterized by the formation of scar tissue within the lungs in the absence of any known cause. "FBN1 was also shown to regulate storage and activation of TGF‐β in the human idiopathic pulmonary fibrosis." (PMID 37635348, 2023). "This revealed an overall increased deposition by AFs of collagen family members (COLs, including COL4A1 and COL11A1), fibrillins (FBN1 and 2) and tenascin (TNC), previously involved in lung fibrosis and deposited by CAFs in other cancers." (PMID 37938546, 2023).
liver fibrosis (3 papers, 2015 to 2023). "FBN1 was reported to involve in ECM organization in liver fibrosis based on bioinformatics analysis." (PMID 37635348, 2023). "Previous reports have shown that FBN1 was remarkably upregulated in several organ fibrosis and related to the development of liver fibrosis." (PMID 37635348, 2023). "Our data suggested that MFAP2 might be involved in liver fibrosis by regulating the expression of FBN1." (PMID 37635348, 2023). "Furthermore, overexpression of FBN1 remarkably restored the cell proliferation and inhibited cell apoptosis as compared to control, suggesting that MFAP2 mediated TGF‐β/Smad3 signalling pathway and fibrotic markers during liver fibrosis by upregulating the expression of FBN1." (PMID 37635348, 2023).
lung carcinoma (3 papers, 2018 to 2025). "In this study, polymorphisms in 3′-untranslated region of IL-16, CYP24A1, and FBN1 were determined in 322 lung cancer patients and 384 healthy controls with the usage of Sequenom MassARRAY." (PMID 30671474, 2018). "Unfortunately, stratified results for gender and age on CYP24A1 rs4809957 and FBN1 rs1042078 did not uncover any associations of these SNPs with lung cancer susceptibility in Chinese Han population (P > 0.05)." (PMID 30671474, 2018).
Marfan lipodystrophy syndrome (3 papers, 2020 to 2024). "Diseases associated with FBN1 were thought to be Marfan lipodystrophy syndrome, and part of the mutation were identified as c.8175_8182del8bp, p.Arg2726Glufs∗9 in exon 64 of the FBN1 gene." (PMID 33083483, 2020).
Marfan-related disorders (3 papers, 2009 to 2012). "The result expands the genotype-phenotype spectrum of FBN1 and helps the study of the molecular pathogenesis of EL and Marfan-related disorders." (PMID 22393277, 2012). "Our data further expand the mutation spectrum of FBN1 and contributes to the study of molecular pathogenesis of MFS and Marfan-related disorders." (PMID 22219643, 2011).
osteoarthritis (3 papers, 2020 to 2022). A noninflammatory degenerative joint disease occurring chiefly in older persons, characterized by degeneration of the articular cartilage, hypertrophy of bone at the margins and changes in the synovial membrane. "In addition, increased expression levels of Fibrillin-1 (FBN1), the major constituent of tissue elastic microfibers and previously identified also in human osteoarthritis synovial fluids, were identified by MS secretome analysis and confirmed by Western blot." (PMID 32466468, 2020).
Osteopenia (3 papers, 2018 to 2023). Osteopenia is a term to define bone density that is not normal but also not as low as osteoporosis. "Meanwhile, blockade of IL4/IL4Rα-mediated mTOR signaling pathway by rapamycin treatment improved osteogenic differentiation in BMSCs, thereby rescuing the osteopenia phenotype in Fibrillin-1 (FBN1)-deficient mice." (PMID 37033227, 2023). "Additionally, fibrillin‐1 (FBN1) was constitutively upregulated in SDEs of osteopenia patients." (PMID 29603567, 2018). "It is speculated that APOA1, FBN1, NOTCH1, SYT7 and KLF10 play key roles in regulating bone metabolic balance and in reversible osteopenia after PAOO, which might be involved in the accelerated tooth movement." (PMID 38012627, 2023). "It is speculated that APOA1, FBN1, NOTCH1, SYT7 and KLF10 played key roles in regulating bone metabolic balance and in reversible osteopenia after PAOO, which might be involved in the accelerated tooth movement." (PMID 38012627, 2023).
osteoporosis (3 papers, 2023 to 2025). A condition of reduced bone mass, with decreased cortical thickness and a decrease in the number and size of the trabeculae of cancellous bone (but normal chemical composition), resulting in increased fracture incidence. "The connective tissue defects caused by fibrillin-1 contribute to skeletal malformation (i.e., lengthening of the limbs, kyphosis, and deformity of the chest wall), and osteoporosis results in fractures of the bone, bone pains, and defects." (PMID 41541920, 2025). "PQQ‐induced Nrf2 activation in osteoblast‐lineage cells increases the cellular stress response and also transcriptionally activates Fbn1, thus reducing the production of Rankl and inhibiting osteoclastic bone resorption, and preventing natural aging‐related osteoporosis." (PMID 37365714, 2023). "PQQ‐induced Nrf2 activation in osteoblast‐lineage cells increases the cellular stress response, and also transcriptionally activates Fbn1, thus reducing the production of Rankl and inhibiting osteoclastic bone resorption, and preventing aging‐related osteoporosis." (PMID 37365714, 2023). "Here, we showed that dietary PQQ supplementation could not only promote bone formation of osteoblasts, but also inhibit bone resorption through the activation of stress response and the upregulation of Fbn1 mediated by MCM3‐Keap1‐Nrf2, thus preventing natural aging‐related osteoporosis." (PMID 37365714, 2023).
periodontal disease (3 papers, 2014 to 2025). "Another ECM molecule, fibrillin-1, whose inactivating mutations are associated with severe periodontal diseases, was also reduced in the PDL of the cKO mice." (PMID 25479552, 2014). "Due to its high fibrillin-1 content, one could predict that the PDL is weakened by FBN1 mutations and thus more susceptible to periodontal diseases." (PMID 40497939, 2025). "MFS has been shown to increase the susceptibility to severe periodontal disease, in association with periodontal ligament dysfunction, due to microfibril insufficiency, suggesting that FBN-1 microfibril formation plays a central role in periodontal ligament formation." (PMID 35945519, 2022). "The hyperactivity of TGFß, which is one major consequence of the fibrillin-1 deficit, is also found in the PDL tissue, and it has been hypothesized that TGFß is involved in the onset of periodontal disease." (PMID 40497939, 2025).
pneumothorax (3 papers, 2011 to 2021). Abnormal presence of air in the pleural cavity. "As expected, a significantly high mortality rate was observed in FBN1 Het rabbits, and pulmonary infections, pneumothorax and ascending aortic dilatation were found in the dead rabbits." (PMID 29666143, 2018). "Furthermore, FBN1 can bound TGFβ and prevent abnormal activation of TGFβ signaling in lung, aorta, and skeletal muscle, which is possibly responsible for many Marfanoid features including pneumothorax." (PMID 33217155, 2021).
retinal detachment (3 papers, 2019 to 2024). An eye emergency condition which may lead to blindness if left untreated. "We describe a pedigree with a FBN1 mutation causing non-syndromic EL with retinal detachment (RRD) and their management." (PMID 31527767, 2020). "Additionally, among surveillance of patients with MFS, up to 10% will develop a retinal detachment, which may be secondary to the elongation of the globe due to decreased fibrillin-1 in the sclera." (PMID 38983985, 2024).
serous ovarian cancer (3 papers, 2021 to 2022). "Studies have reported that high expression of FBN1 decreases the OS of serous ovarian cancer, and it increases the risk of lymph node metastasis." (PMID 33563317, 2021). "Six mutations on the FBN1 gene were identified in cases of serous ovarian cancer." (PMID 34386072, 2021). "Moreover, FBN1 is linked with worse overall survival, as well as advanced stage of disease in high grade serous ovarian cancer." (PMID 34386072, 2021).
Stroke (3 papers, 2020 to 2024). Sudden impairment of blood flow to a part of the brain due to occlusion or rupture of an artery to the brain. "Key EMT-related genes that were downregulated upon MMP-3 KO in male stroke brains included Fbn1, Fbln1, Tgfb1, Tgfbr3, Snai2, and Fgf2." (PMID 39000490, 2024). "Both male and female MMP-3 KO stroke brains showed decreased expression of genes involved in fibulin signaling (Fbln1, Fbn1, Fbln2, Fbln5), which are known to induce EMT during embryonic development." (PMID 39000490, 2024). "Apart from pathogenic or likely pathogenic findings, 41 rare VUS in 325 stroke-related candidate genes were detected in 39 probands, including eight novel variants: ABCA1 p.H1223P, ACTA2 p.N298S, COL5A1 p.P930R, FBN1 p.Q514E, FBN1 p.K1052T, GP1BA p.P437*, RNF213 p.N1631Efs*34, and TSC1 p.P397del." (PMID 36580209, 2023). "Key EMT-related genes that were downregulated in MMP-3 KO males included Fbn1, Fbln1, Tgfb1, Tgfbr3, Snai2, and Fgf2, while female MMP-3 KO stroke brains showed downregulation of Fbln5, Fbln1, Fbln2, and Tgfb1." (PMID 39000490, 2024).
Ventricular arrhythmia (3 papers, 2013 to 2024). "Of note, 5 patients with FBN1 mutation exhibited early repolarization, which was unrelated with ventricular arrhythmia." (PMID 24349050, 2013). "Large multi-centre trials should investigate risk factors and preventive and therapeutic options for FBN1 gene-related ventricular arrhythmia." (PMID 24349050, 2013). "The study shows that adults with FBN1 gene mutations have a high prevalence both, of ventricular arrhythmia on baseline AECG (48%) and of VTE (8%) including SCD (4%) during follow-up." (PMID 24349050, 2013). "Thus, we performed this observational cohort study of adults with FBN1 gene mutations to elucidate the impact of both clinical characteristics and FBN1 mutation characteristics on the risk of ventricular arrhythmia and SCD." (PMID 24349050, 2013). "Consequently, clinical and molecular risk factors of ventricular arrhythmia require further investigation in large multi-centre trials of patients with FBN1 mutations using advanced monitoring technology such as loop recorders." (PMID 24349050, 2013). "Thus myocardial dysfunction emerges as a risk for ventricular arrhythmia in FBN1 mutations." (PMID 24349050, 2013). "With FBN1 mutations located in exons 24–32 MFS exhibits both, more pronounced aortic root disease and more frequent ventricular arrhythmia events." (PMID 25491897, 2014).
abdominal aortic aneurysm (2 papers, 2019 to 2023). Enlargement and ballooning of the vessel that supplies arterial blood to the abdomen, pelvis and legs. "In conclusion, FBN1 variant c.1453C>T, p.(Arg485Cys) is a pathogenic variant that can cause autosomal dominant Marfan syndrome characterized by a high degree of clinical variability and apparently isolated early onset familial abdominal aortic aneurysms." (PMID 30485715, 2019).
Aortic Rupture (2 papers, 2024 to 2025). The tearing or bursting of the wall along any portion of the AORTA, such as thoracic or abdominal. "Many snapshot studies on aneurysmal tissue mechanics leverage Fbn1 mgR/mgR mice that exhibit a severe MFS phenotype and die spontaneously of aortic rupture by 9 weeks-of-age." (PMID 38545339, 2024).
atrial fibrillation (2 papers, 2024 to 2025). A disorder characterized by an electrocardiographic finding of a supraventricular arrhythmia characterized by the replacement of consistent P waves by rapid oscillations or fibrillatory waves that vary in size, shape and timing and are accompanied by an irregular ventricular response. "On one hand, they reported that atrial arrhythmia (atrial fibrillation/atrial flutter) is most common in patients with (L.)pathogenic variants affecting FBN1 compared to patients with (L.)pathogenic variants in other TGF-β signaling genes." (PMID 38667733, 2024).
Autoimmunity (2 papers, 2005 to 2022). The occurrence of an immune reaction against the organism's own cells or tissues. "A fibrillin-1 (Fbn1)-target knock-in mutant mice displayed several features of a systemic sclerosis-like disease, including skin fibrosis, immune cell activation, and autoimmunity with antinuclear and anti-topoisomerase I antibodies, but did not develop microvascular changes." (PMID 35629370, 2022).
colon adenocarcinoma (2 papers, 2021 to 2022). "The data presented in our study support these findings as methylation of FBN1 is significantly higher in colon adenocarcinoma (COAD) compared to healthy colon." (PMID 34386072, 2021). "FBN1 methylation in colon adenocarcinoma (COAD) is significantly higher than healthy colon." (PMID 34386072, 2021).
colorectal adenoma (2 papers, 2011 to 2021). An adenoma that arises from the colon or rectum. "We have identified four genes, CNRIP1, FBN1, INA, and SNCA that were frequently hypermethylated in colorectal adenomas and cancers." (PMID 21777459, 2011).
depression (2 papers, 2021 to 2024). "Using data from the Taiwan Biobank, a novel SNP, rs192922209, located in the intron region of the FBN1 gene on chromosome 15, was associated with depression." (PMID 39028994, 2024).